H19 (H19 imprinted maternally expressed transcript)
Diseases named in the same sentence as H19 in open-access papers (continued):
Sharing a sentence is not in itself a finding about the gene and the disease.
ovarian carcinoma (continued). "Actually, the first discovered abnormal expression lncRNA in ovarian cancer was the imprinted maternally expressed H19 gene." (PMID 29921308, 2018). "Although there were no statistical differences between the two groups of higher and lower H19 expression in breast or ovarian cancer, there was an “HR >1” in almost all of our analyses of breast and ovarian cancer." (PMID 27926484, 2017). "Other lncRNAs have also been shown to be associated with ovarian cancer development and metastasis, including HOTAIR, H19, GAS5, and UCA1; however, to date, little was known about linc-ROR in ovarian cancer." (PMID 29050257, 2017). "H19-DTA (BC-819) is a DNA plasmid that drives the expression of the diphtheria toxin gene under the regulation of the H19 promoter sequence and therefore is a potential treatment for various tumors that overexpress the H19 gene, among them—ovarian cancer." (PMID 28154921, 2017). "H19 is overexpressed in a number of drug-resistant cell lines, including doxorubicin-resistant liver cancer cells and cisplatin-resistant ovarian cancer A2780-DR cells." (PMID 28933364, 2017). "In the cisplatin-resistant ovarian cancer cells, H19 knockdown coincided with a reduction of glutathione S-transferase P1 (GSTP1), responsible for cisplatin inactivation." (PMID 28933364, 2017). "H19 knockdown has been shown to inhibit the growth and clonogenicity of epithelial ovarian cancer cells in a synergic manner with histone H1.3 overexpression." (PMID 27664137, 2017). "In ovarian carcinoma, it was shown that a chemoresistant A2780 cell line expressed higher levels of H19 than the sensitive counterpart and this observation was associated with a mesenchymal phenotype in the resistant cell line." (PMID 26992233, 2016). "Using an ovarian cancer model (A2780), we showed that Slug induces H19 expression and activates its promoter." (PMID 26623562, 2016). "The cell-specific expression of the DT-A chain driven by the H19 promoter region was shown to kill cancer cells in a variety of targeted indications, i.e. bladder, pancreatic, and ovarian cancers, as well as cancers metastatic to the liver." (PMID 26623562, 2016). "In ovarian cancer and uterine serous carcinoma cell lines, the pro metastatic oncogene c-Myc, which upregulates H19, is also its indirect target, due to removal of c-Myc let-7-mediated repression." (PMID 26536864, 2015). "The anti-diabetic drug Metformin can vitiate the metastatic phenotype of ovarian cancer cell lines, apparently due to induction of hypermethylation at the H19 locus." (PMID 26536864, 2015). "The therapeutic potential of a vector carrying the DT-A gene driven by H19 regulatory sequences was tested both in ovarian cancer cell lines and in a subcutaneous nude mice model for ovarian cancer." (PMID 19656414, 2009). "The present work shows the use of the regulatory sequences of the H19 gene for the development of DNA-based therapy for human ovarian cancer related ascites." (PMID 19656414, 2009). "The high level of H19 RNA found in the OCAF is in accordance with previous results obtained from our study on the expression profile of H19 in epithelial ovarian cancer." (PMID 19656414, 2009). "H19 RNA is present at high levels in human cancer tissues (including ovarian cancer), while existing at a nearly undetectable level in the surrounding normal tissue." (PMID 19656414, 2009). "The goal of the present study was to evaluate the therapeutic potential of expression vectors carrying the "A" fragment of the diphtheria toxin (DT-A) gene under the control of the H19 regulatory sequences in an ovarian carcinoma animal model." (PMID 19656414, 2009). "Detection of H19 expression in epithelial ovarian cancer using ISH technique revealed that H19 is expressed in the majority of serous epithelial tumors." (PMID 19656414, 2009).
ovarian carcinoma (continued). "Positive correlations were identified between elevated IGF2 expression and hypermethylation of CTCF binding sites at the H19 proximal imprint center in ovarian cancer." (PMID 19737423, 2009). "To evaluate the possible use of H19 regulatory sequences for the therapy of ovarian cancer, we determined the level of H19 transcripts in cells from ascites fluid of women patients." (PMID 19656414, 2009). "The H19 regulatory sequences were able to drive DTA expression in the ovarian cancer cell lines that led to cell death." (PMID 19656414, 2009). "Based on these results, we decided to further investigate the use of H19 regulatory sequences for driving toxin gene expression in a therapeutic vector for ovarian cancer." (PMID 19656414, 2009). "Similarly, in ovarian cancer, H19 acts as an oncogenic lncRNA by sponging miR-17 to enhance NF-κB signaling —mirroring its role in adenomyosis." (PMID 41226749, 2025). "The H19/miR-140/Wnt1 axis is pivotal in promoting proliferation and migration in ovarian cancer." (PMID 38166752, 2024). "Moreover, H19 is involved in the TGF-β/H19/miR-370-3p/EMT signaling axis in ovarian cancer progression." (PMID 38166752, 2024). "In addition to hematologic malignancies, other investigations also reportedoverexpression of H19 in numerous solid cancers such as hepatic, bladder,gastric, lung, and ovarian cancers." (PMID 36680478, 2023). "The lncRNA H19 promoter sequence has been introduced with the coding sequence of diphtheria toxin in BC-819 plasmid in clinical trials of the bladder, pancreatic and ovarian cancer." (PMID 37568568, 2023). "This approach could be considered efficient against ovarian cancer, as 90% of patients with ovarian cancer ascites fluid present with H19 RNA." (PMID 35744957, 2022). "H19 is significantly increased in ovarian cancer cells and ovarian cancer tissues." (PMID 35103065, 2022). "H19/miRNA-140 axis promotes ovarian cancer cell migration by upregulating Wnt1 expression." (PMID 36310592, 2022). "Some studies have shown that the level of lncRNA-H19 is abnormally elevated in ovarian cancer tissues, and H19 may be involved in the cisplatin resistance of EOC cells." (PMID 34475985, 2021). "Additionally, Rg3 can inhibit the Warburg effect in ovarian cancer cells using the H19/miR-324-5p/PKM2 axis." (PMID 33805687, 2021). "In addition, lncRNA H19 overexpression in ginsenoside 20(S)-Rg3-treated ovarian cancer cells increases glucose consumption, lactate production and pyruvate kinase isozyme M2 (PKM2) expression." (PMID 33652661, 2021). "Similarly, data has suggested that the lncRNA RNA H19 is overexpressed in breast, cervical, and ovarian cancers." (PMID 35011637, 2021). "Similarly, H19 targeted therapy is under phase I/II clinical trials in bladder, pancreatic and ovarian cancer patients." (PMID 31141943, 2019). "Recent study investigated that H19 was associated with OS and DFS in ovarian cancer." (PMID 29921308, 2018). "H1.3 is a specific repressor for the noncoding oncogene H19 in ovarian cancer, where H1.3 overexpression occupies the H19 regulator region encompassing the imprinting control region (ICR), along with increased DNA methylation and reduced binding of the insulator protein CTCF at the ICR." (PMID 30176860, 2018). "In addition, silencing H19 induced apoptosis through mitochondrial and caspases dependent pathway in ovarian cancer cell lines." (PMID 29921308, 2018). "In ovarian cancer cells, H19 overexpression enhances migration and invasion." (PMID 28637507, 2017). "In ovarian cancer cells, it was shown that H19 overexpression enhances migration and invasion." (PMID 26992233, 2016). "We have found that H19 is highly expressed in ovarian cancer patients that have short RFS." (PMID 27193186, 2016). "Furthermore, the role of H19 in metastasis was elucidated later in ovarian cancer cells were H19 was discovered to interfere with let-7 mediated downregulation of MYC mRNA and protein levels." (PMID 27077133, 2015).
ovarian carcinoma (continued). "Association of drug resistance with elevated levels of H19 and Slug was demonstrated in a cisplatin resistant ovarian cancer cell line, in which H19 upregulates, apparently indirectly, the promoter activity of Slug, which upregulates H19 in a positive feedback loop." (PMID 26536864, 2015). "We determined the level of H19 RNA in different human ovarian cancer cell lines." (PMID 19656414, 2009). "Likewise in ovarian cancer, lncRNA H19 modulates various genes and pathways and suppresses miR-612, miR-342-3p, miR-124-3p and miR-216a-5p modulating HOXA10, IER3, ITGB3 and ACTA2 and influencing endometrial cancer cell viability, invasion and overall survival." (PMID 39912983, 2025). "In addition, Zhu et al16 found that silencing H19 can inhibit the proliferation of ovarian cancer SKOV3 cells and is related to the regulation of certain cell cycle‐ and apoptosis‐related proteins, thus exerts an inhibitory effect on ovarian cancer cell growth." (PMID 33236528, 2021). "Whether H19 directly regulates miR-140-5p in ovarian cancer cells has been unclear." (PMID 34250088, 2021). "Additionally, recent report was indicating that H19 may be predictive of responsiveness to ovarian cancer therapy." (PMID 29921308, 2018). "Besides, H19 RNA has been detected in the majority of patients with ovarian cancer ascites fluid." (PMID 27664137, 2017). "Therefore, more detailed studies on the role of H19/miR-675 might be of interest owing to the chemoresistance and peritoneal invasion usually observed in ovarian carcinoma." (PMID 26992233, 2016). "However, H19 was highly expressed in cancer tissues (p = 0.0036) and showed a significant relationship with RFS (p = 0.0142), indicating that HGSC patients with higher H19 expression levels had higher risk of ovarian-cancer recurrence." (PMID 27193186, 2016). "Several lncRNAs like ZFAS1, MALAT1, H19 have been shown to increase resistance to cisplatin while lncRNA like GAS5, NEAT1 lower cisplatin resistance in ovarian cancer cells." (PMID 39912983, 2025). "Here, we review NEAT 1, SOX21-AS1, H19, 74 LOXL1-AS1, MAFG-AS1, GAS5 and LINC0015 long non-coding RNAs because of their involvement in ovarian cancers." (PMID 39337410, 2024). "In the cisplatin-resistant ovarian cancer cell line OVCAR3/DDP, the expression level of H19 was found to be significantly increased compared to the OVCAR3 cell line." (PMID 38166752, 2024). "These researchers further observed decreased expression of HOTAIR, bcl-2, and H19, along with overexpression of MEG3, after treating ovarian cancer cells with DNC, indicating that curcumin exerts its anticancer effects via multiple pathways." (PMID 39830662, 2024). "Treatment with lncRNA H19, MAFG-AS1 or GAS5 is a promising treatment for ovarian cancer, although further research is needed in this area." (PMID 39337410, 2024). "Among others, lncRNA HOTAIR, H19, MALAT1, and HOST2 can be used as potential therapeutic targets for ovarian cancer and are closely related to tumorigenesis and metastasis in ovarian cancer." (PMID 35706412, 2022). "The use of double promoter toxin vector H19-DTA-(IGF2)-P4-DTA exhibited superior inhibition towards pancreatic cancer, ovarian cancer, glioblastoma and HCC." (PMID 36246634, 2022). "In our previous studies of human endometrial cancer and ovarian cancer cells, we showed that H19 positively regulates HMGA2 expression via the H19/let-7 axis." (PMID 31089260, 2019). "A qualitative evaluation of ovarian cancer revealed the top 20 predictions by LION contained all four experimentally validated lncRNAs: MALAT1, H19, HOTAIR, and PVT1." (PMID 31379598, 2019). "Many lncRNAs, such as HOTAIR, H19, MEG3, and UCA1, have been recognized as key regulators of the occurrence and development of ovarian cancer." (PMID 29050257, 2017). "Examples include some well-known lncRNAs, some of which are involved in ovarian cancer biology such as PVT1 and H19." (PMID 26992233, 2016).
ovarian carcinoma (continued). "H19-DTA was also found to be effective in ovarian carcinoma cell lines and in a heterotopic animal model for ovarian cancer." (PMID 23984081, 2013). "In order to determine the feasibility of this approach for the therapy of ovarian cancer in a human patient, both RT-PCR and ISH analyses were applied on cells isolated from OCAF to determine the level of H19 gene expression." (PMID 19656414, 2009). "In in vivo condition a mechanism has revealed which is independent of the H19–let–7 axis in EC and ovarian cancer which results in the co-expression of H19 and certain oncogenes." (PMID 39912983, 2025). "Previous evidence revealed that H19 and miR-140-5p are abnormally expressed and may affect the EMT of ovarian cancer cells." (PMID 34250088, 2021). "Interestingly, H19 can target miR-324-5p to increase pyruvate kinase M2 (PKM2) expression and glucose metabolism, and support the growth of ovary cancer." (PMID 32272875, 2020). "Moreover, MALAT1, NEAT1, GAS5, H19 and XIST have been experimentally validated to be ovarian cancer-related lncRNAs, which were identified as hubs that connect 26, 15, 22, 20 and 9 modules in OV dataset, respectively." (PMID 30732558, 2019). "In addition, H19 sequestering of let-7 is required for H19 to function in EMT processes such as cell invasion and migration in ovarian cancer, as well as in uterine serous carcinoma cell lines." (PMID 28637507, 2017). "However, in the context of ovarian carcinoma, HOST2 and H19 lncRNAs can act as ceRNA toward let-7b, thereby “sponging” its effects." (PMID 26992233, 2016). "Interestingly, knockdown of lncRNA H19 in A2780/CDDP cells restored cisplatin sensitivity reducing NQO1 and NRF2 expression, proving that lncRNA H19 has a pivotal role in cisplatin resistance of ovarian cancer cells modulating NRF2/NQO1 signaling." (PMID 37175546, 2023). "H19 and MALAT1 may play a suppressive role in ovarian cancer metastasis." (PMID 24379988, 2013). "We suggest that DNA methylation of H19 and PEG1 differentially methylated regions (DMRs) may provide novel biomarkers useful for screening, diagnosis and, potentially, for improving the clinical management of women with human ovarian cancer." (PMID 22443985, 2012). "Also, phase I/II clinical trials are underway in patients with bladder, pancreatic and ovarian cancers for lncRNA H19 targeted therapy based on in vitro experiments demonstrating tumor cell growth arrest without affecting normal cells with H19 promoter cloned into BC-819 plasmid." (PMID 28969100, 2017).
glioblastoma (67 papers, 2014 to 2025). The most malignant astrocytic tumor (WHO grade IV). "For example, lncRNA H19 recruited tumor-associated macrophages, leading to T cell exhaustion and the remodeling of immune microenvironment in glioblastoma." (PMID 39925803, 2025). "The possible underlying mechanisms for H19-mediated MDR in glioblastoma are the overexpression of MDR, MRP, and ATP-binding cassette superfamily G member 2 (ABCG2)." (PMID 33806782, 2021). "A previous study found that hypoxia played a crucial role in increasing H19 expression in glioblastoma cells, which was associated with HIF-1α." (PMID 30458806, 2018). "In the central nervous system (CNS), H19 is significantly overexpressed in glioblastoma tissues and its expression level is associated with patient survival." (PMID 29795132, 2018). "Furthermore, H19 promotes invasion and angiogenesis in glioblastoma, and its overexpression is associated with poor overall survival and progression-free survival." (PMID 39015773, 2024). "A manual survey of the GeneCards database and the literature on glioblastoma revealed that both clusters were characterized by some genes involved in cancer (e.g. H19 for C.L.1 and IGFBP2 for C.L.L.L)." (PMID 40491972, 2025). "The imprinted oncofetal lncRNA H19, originating from a paternally imprinted gene, is among the earliest identified upregulated lncRNAs observed across various cancer types, including glioblastoma." (PMID 39015773, 2024). "LncRNA H19 is also at the stage of clinical trials for glioblastoma, ovarian, bladder, and pancreatic cancer." (PMID 37958880, 2023). "Upon hypoxia, hypoxia-inducible factors (HIFs) modulate many ncRNAs, including MALAT1, the lncRNA HOTAIR in non-small cell lung cancer (NSCLC), and the lncRNA H19 in glioblastoma." (PMID 36012617, 2022). "Activation of the NF-κB signaling pathway is considered as another mechanism for H19-mediated MDR in glioblastoma." (PMID 33806782, 2021). "Invasion and metastasis: in-vitro Matrigel invasion assay showed that overexpression of H19 enhanced the invasiveness of glioblastoma cells." (PMID 34322395, 2021). "Histological classification of pedHGG samples showed that DIPG tissues express higher H19 levels than other pedHGGs, including anaplastic astrocytoma and glioblastoma (p < 0.01)." (PMID 34502082, 2021). "H19 binds EZH2 in glioblastoma cells, and that EZH2 binding to NKD1 and other promoters is impaired by H19 silencing." (PMID 34296520, 2021). "One of the roles of H19 is to contribute to glioblastoma malignancy and to maintain the glioblastoma stem-cell properties." (PMID 32650527, 2020). "The increased expression of H19 promotes glioblastoma cell migration, angiogenesis, stemness, and tumorigenicity." (PMID 32650527, 2020). "H19 plays an important role in glioblastoma tumorigenicity, since its overexpression promotes invasion, angiogenesis, stemness and increased tumor growth in vivo." (PMID 32283739, 2020). "Hypoxia-inducible factor 1-alpha (HIF-1α) directly promotes H19 expression under hypoxia in glioblastoma cells." (PMID 32650527, 2020). "In glioblastoma, knockdown of H19 expression leads to decreased cellular proliferation and a higher apoptotic rate after induction by chemotherapy (temozolomide)." (PMID 33291403, 2020). "This is the proof that H19 expression reinforces both stemness and chemoresistance of glioblastoma cells." (PMID 33291403, 2020). "Not surprisingly, scholars have revealed that aberrant expression of lncRNA H19 and miR-215 in glioblastoma confers a poor prognosis for patients." (PMID 32014012, 2020). "In the CNS, H19 is overexpressed in glioblastoma tissues and it promotes the invasion, angiogenesis, proliferation, and migration of glioblastoma cells." (PMID 31581735, 2019). "H19 knock-down reduces viability, migration and invasiveness of two distinct human glioblastoma cell lines." (PMID 29643989, 2018).